HLA-G (major histocompatibility complex, class I, G)
Diseases named in the same sentence as HLA-G in open-access papers (continued):
Sharing a sentence is not in itself a finding about the gene and the disease.
ovarian carcinoma (continued). "Consistent with previously published studies conducted with other cancer cell lines, our results suggest that the methylation status of the HLA-G promoter region may be important for the control of HLA-G expression in ovarian cancer." (PMID 18498645, 2008). "Previously, our in vitro studies provided that HLA-G expression in hepatocellular carcinoma and ovarian carcinoma cell lines could directly inhibit NK cell lysis, and blocking with HLA-G antibodies restored the NK-mediated lysis of the targeted cancer cell lines." (PMID 34276642, 2021). "Thus, the beneficial effects that HLA-G expression might have had in ovarian carcinoma patients possibly depended on HLA-A co-expression." (PMID 34361031, 2021). "Upregulation of MMP15 by HLA-G might result in invasiveness or metastasis of ovarian cancer." (PMID 32887509, 2020). "HLA-G CAR-transduced NK cells present effective cytolysis of breast, brain, pancreatic, and ovarian cancer cells in vitro, as well as reduced xenograft tumor growth with extended median survival in orthotopic mouse models." (PMID 34663641, 2021). "Lately, HLA-G bearing EV (HLA-GEV) originated from liquid biopsies of blood samples derived from breast and ovarian cancer patients have been introduced as novel cancer biomarker." (PMID 32973812, 2020). "In various cancers, de novo HLA-G expression has been observed, including in colorectal cancer (CRC), breast cancer, melanoma and ovarian cancer." (PMID 33213057, 2020). "It has been observed that HLA-G expression in ovarian cell line upregulates matrix metalloproteinase 15 (MMP-15) expression in these cells and a correlation between HLA-G and MMP-15 expression is also seen in ovarian cancer patients." (PMID 33213057, 2020). "HLA-G exhibited a strong co-localization with CA125 in ovarian cancer, indicating that HLA-G might be a valuable predictive biomarker for early ovarian cancer." (PMID 38310272, 2024). "All other studies did not demonstrate correlations between tumour HLA-G expression and factors indicative for increased tumour burden in ovarian carcinoma patients." (PMID 34361031, 2021). "Histological sections of TNBC, GBM, pancreatic cancer (PA), and ovarian cancer (OV) showed strong cell membrane and cytosolic staining of HLA-G, which were absent from paired peritumoral healthy tissues." (PMID 34663641, 2021). "Expression of the non-classical human leukocyte antigen-G (HLA-G) promotes cancer progression in various malignancies including epithelial ovarian cancer (EOC)." (PMID 30932005, 2019). "With an immunodeficient murine ovarian cancer xenotumor model, we found that HLA-G1 expressing ovarian cancer cells had stronger invasion and metastasis potential compared that with the HLA-G-negative parental cells." (PMID 30234020, 2018). "In our study we looked at the same region in the ovarian cancer cell line BG-1, which showed almost complete methylation of all CpG dinucleotides and no expression of HLA-G." (PMID 18498645, 2008). "To determine if ovarian tumor cells would show a similar response, we selected an ovarian cancer cell line (BG-1) that did not display HLA-G expression prior to treatment." (PMID 18498645, 2008). "Unlike detected with mAb 4H84, HLA-G expression detected with mAb 5A6G7 was also found to unrelated to clinical parameters such as FIGO stage and prognosis in ovarian cancers." (PMID 30234020, 2018).
autoimmune disease (38 papers, 2008 to 2026). A disorder resulting from loss of function or tissue destruction of an organ or multiple organs, arising from humoral or cellular immune responses of the individual to their own tissue constituents. "The HLA-G 14 bp variant has been related to various diseases, including autoimmune diseases, infectious diseases and cancer." (PMID 38391781, 2024). "In recent years, Human Leukocyte Antigen-G (HLA-G) has become a research hotspot in studying the relationship between cancer risk and certain autoimmune diseases." (PMID 38818502, 2024). "Recent studies demonstrated important immunomodulatory effects of HLA-G expression and its role in tumors, inflammatory processes and autoimmune diseases, transplantation and for recurrent spontaneous abortions of embryos in HLA-G-deficient women." (PMID 27057628, 2016). "The common polymorphism of the HLA-G seems to affect its level of expression and may have an impact on disease susceptibility in autoimmune disorders." (PMID 27610404, 2016). "However, overexpression of HLA-G is induced under multiple pathological conditions, including malignant tumors, viral or microbial infections, and autoimmune diseases Convergent data implicated that HLA-G was enriched in several tumors, thereby fueling the immune evasion." (PMID 38310272, 2024). "The ability of HLA-G to limit the progression of these diseases has been confirmed and, in fact, levels of the molecule and several of its polymorphisms have been associated with increased susceptibility to the development of autoimmune diseases, as well as increased disease severity." (PMID 35154112, 2022). "We further summarize current strategies that incorporate or target HLA-G in the treatment of malignancies and autoimmune diseases, and highlight its emerging potential as a therapeutic target." (PMID 41445738, 2025). "The role of HLA-G has been extensively studied in various inflammatory conditions, especially in autoimmune diseases such as hypothyroidism." (PMID 38818502, 2024). "Numerous studies have investigated the expression of HLA-G in both cancer and autoimmune diseases, highlighting its clinical significance." (PMID 37627278, 2023). "For a comprehensive exploration of the role of HLA-G in other autoimmune diseases, please refer to the review by Contini." (PMID 37627278, 2023). "In autoimmune diseases, HLA-G plays a role in immune system regulation, and its polymorphisms have been strongly associated with susceptibility to these conditions." (PMID 37627278, 2023). "This hypothesis is further supported by frequent HLA-G association with other autoimmune diseases, such as lupus erythematosus systemic, Crohn’s disease, multiple sclerosis, rheumatoid arthritis, and pemphigus vulgaris, along with HLA-G ectopic expression in skin pathologies." (PMID 36831297, 2023). "HLA-G expression is frequently observed in tumors as well as various autoimmune diseases, suggesting its potential involvement in the pathogenesis of these conditions." (PMID 37627278, 2023). "Although the role of HLA-G in tumor immune escape and autoimmune diseases has been extensively explored, it is particularly relevant to pregnancy, where it plays a crucial role in immune tolerance." (PMID 37627278, 2023). "In the case of multiple sclerosis (MS), an autoimmune disease that targets the central nervous system and leads to demyelination, there is mounting evidence of the high expression of HLA-G in immune cells found in the cerebrospinal fluid of MS patients." (PMID 37627278, 2023). "Due to the relevant implications of HLA-G in cancer and autoimmunity, we will describe in detail the most relevant studies of HLA-G in different tumor types and autoimmune diseases in the next sections of this review." (PMID 35154112, 2022).
autoimmune disease (continued). "In depth knowledge of the function of HLA-G opens the possibility of establishing new immunomodulatory therapeutic approaches in cancer (new immune checkpoint inhibitors) or in autoimmune diseases (modulating the levels of this molecule)." (PMID 35154112, 2022). "HLA-G deregulation is also important in pathological situations such as tumors and autoimmune diseases." (PMID 34845256, 2021). "The pertinence of HLA-G has been investigated in numerous studies which have sought to elucidate the relevance of HLA-G in pathologic conditions, such as autoimmune diseases, cancers, and hematologic malignancies." (PMID 34948145, 2021). "On the other hand, the use of recombinant HLA-G would be a plausible alternative for allograft and autoimmune disease treatment." (PMID 34845256, 2021). "The role of HLA-G+ immune cells in the context of autoimmune diseases will be discussed in the following paragraphs." (PMID 32983083, 2020). "Recent studies have also revealed that HLA-G is involved in the progression of cancer cells and the protection from autoimmune diseases." (PMID 31779209, 2019). "HLA-G plays a role in fetal-maternal tolerance as well as immunoregulation, and has been suggested to be involved in autoimmune diseases and cancers." (PMID 27331404, 2016). "Genetic interaction between LILR and HLA-G genotypes involved in the occurrence of autoimmune diseases will be an intriguing subject of study in the future." (PMID 27331404, 2016). "Mounting evidence designates that HLA-G plays a role in the regulation of inflammatory processes and autoimmune diseases." (PMID 27610404, 2016). "Growing evidence indicates that HLA-G plays a role in the regulation of inflammatory processes and autoimmune diseases." (PMID 25853899, 2015). "In recent years, a substantial number of scientific studies have indicated that the expression of HLA-G plays a role in the regulation of inflammation in autoimmune diseases." (PMID 25853899, 2015). "Only few data are present in the literature regarding the role of both HLA-G and -E in inflammatory/autoimmune diseases." (PMID 25202308, 2014). "The top three ranked genes, HLA-G, TAP2 and HLA-DRB1, are implicated in autoimmune diseases, while TAP2 is associated with SNPs characteristic for MG." (PMID 18851734, 2008). "Additionally, HLA-G agonists or engineered cells are being explored for inducing tolerance in autoimmune diseases and transplantation." (PMID 41800033, 2026). "It is believed that the weakening of the immune suppressive state is one of the factors leading to the development of autoimmune diseases, and HLA-G may serve as a mechanism to counteract the damage in these diseases." (PMID 38818502, 2024). "As a tolerogenic molecule, HLA-G seems to be protective in presence of inflammation or in autoimmune diseases, whereas conversely, HLA-G allows tumoral disease progression, inducing a state of immunotolerance for cancer cells where it can be neo-expressed and promote cancer progression." (PMID 36768880, 2023). "Furthermore, HLA-G is important in organizing immune responses and maintaining the tolerance in inflammatory and autoimmune diseases." (PMID 35628346, 2022). "Also, in recent years, several studies have shown that HLA-G plays an important role in the control of autoimmune diseases." (PMID 35154112, 2022). "Previous studies have described the pathways of HLA-G-induced tolerance and the role that these molecules play in autoimmune diseases, such as rheumatoid arthritis and systemic lupus erythematosus, but so far, no studies have investigated the impact of HLA-G expression on autoimmune hepatitis." (PMID 36311782, 2022). "Scientific research shows that HLA-G expression can be induced under pathological conditions such as: neoplastic transformation, viral infections, inflammation, promoting transplant tolerance, and autoimmune diseases." (PMID 34948145, 2021). "Another autoimmune disease involving HLA-G molecules is systemic lupus erythematosus (SLE)." (PMID 34948145, 2021).
autoimmune disease (continued). "The data collected and presented in this review article were intended to emphasize the significant influence of HLA-G molecules on the development and course of selected autoimmune diseases, including the gastrointestinal tract, respiratory system, rheumatoid diseases, and type 1 diabetes mellitus." (PMID 34948145, 2021). "Quantitative and qualitative derangements of HLA-G+ immune cells have been detected in several conditions in which the immune system plays an important role, such as infectious, neoplastic, and autoimmune diseases as well as in complications from transplants and pregnancy." (PMID 32983083, 2020). "Therefore, HLA-G is a prominent drug candidate for autoimmune diseases, and HLA-Gs-LILR interactions are also one of the targets for cancer immune therapy." (PMID 31779209, 2019). "Soluble HLA-G is influenced by many other conditions, for example, cancer and autoimmune disease, which may confound the analysis and the results and reduce the suitability of sHLA-G as a biomarker for LVSD." (PMID 27800497, 2016). "In normal conditions, HLA-G molecule is expressed in the thymus, cornea and nail matrix but in other tissues, they are expressed in pathological conditions such as tumor lesions, inflammation, autoimmune diseases, and viral infections." (PMID 27757202, 2016). "Although previous reports demonstrated association of HLA-G 14bp indel with SLE and various autoimmune diseases including celiac disease, pemphigus vulgaris and multiple sclerosis, the genetic association as well as its functional consequences are not yet established." (PMID 27331404, 2016). "Thus, our findings would also have an application for autoimmune diseases in which HLA-G plays an important role, as demonstrated in Multiple Sclerosis and in coeliac diseases." (PMID 26460949, 2015). "In fact, HLA-G may exhibit two distinct effects in pathological conditions: it could be protective in inflammatory and autoimmune diseases or it could be dangerous, for example, in tumors or infectious diseases." (PMID 24818168, 2014). "Thus, modulating HLA-G expression in target tissues of oncology patients or patients with autoimmune diseases may be potential therapeutic approaches to treat these pathological conditions." (PMID 35154112, 2022). "Understanding the characteristics of HLA-G in immunologic tolerance is not only beneficial for pathological pregnancy, but also helpful to the therapy of other immune-related diseases, such as organ transplant rejection, tumor migration, and autoimmune disease." (PMID 34777357, 2021). "Since HLA-G antigens are currently considered as immunomodulatory molecules that are involved in reducing inflammatory and immune responses, in this review, we decided to focus on this group of antigens as potential determinants of progression in autoimmune diseases." (PMID 34948145, 2021). "Because HLA-G antigens are currently considered immunomodulatory molecules that are involved in reducing inflammatory and immune responses in the human body, in this review, we decided to focus on this group of antigens as potential determinants of the progression of autoimmune diseases." (PMID 34948145, 2021). "Notably, the amounts of HLA-G inversely correlate with the severity of autoimmune diseases." (PMID 31779209, 2019). "While there is a little variability in HLA-G coding region and protein, both promoter and 3’ untranslated (3’UTR) regions bear polymorphisms which affect the levels of HLA-G expression, and some have been associated with different pathologies such as cancer and autoimmune diseases." (PMID 31759373, 2019). "Consequently, alterations in the HLA-G system might be a possible mechanism involved in the etiology of this autoimmune disorder." (PMID 22654952, 2012). "Recently, antibodies directed against non-classical HLA molecules, HLA-G, -E, and -F have been detected in autoimmune diseases, like systemic lupus erythematosus." (PMID 38003669, 2023).
autoimmune disease (continued). "An ectopic expression of HLA-G molecules has been observed during “no-physiological” conditions, such as viral infection, cancer, transplantation, and in inflammatory and autoimmune diseases." (PMID 24818168, 2014). "Recent studies have demonstrated the altered expression of HLA-G in autoimmune diseases, such as multiple sclerosis, rheumatoid arthritis, and systemic lupus erythematosus (SLE), suggesting a role for this molecule in the pathophysiology of autoimmune diseases." (PMID 22654952, 2012).
colorectal cancer (35 papers, 2011 to 2025). A primary or metastatic malignant neoplasm that affects the colon or rectum. "Overexpression of HLA-G has been linked with many types of cancers, including breast, ovarian, lung, renal, gastric, and colorectal cancer, and hematological malignancies." (PMID 39594832, 2024). "Our meta-analysis is the first to validate the association between HLA-G expression and prognosis in patients with colorectal cancer using bioinformatics." (PMID 37875821, 2023). "Recently, HLA-G expression has been associated with a worsened prognosis in patients with colorectal cancer." (PMID 35027037, 2022). "In total, eight studies described the association between HLA-G expression and clinical outcome in colorectal carcinoma (CRC) patients." (PMID 34361031, 2021). "In conclusion, +3035 C>T and in particular, +2960 14-bp INDEL and +3187 A>G polymorphisms in the regulatory 3’UTR of the HLA-G gene, have emerged as novel prognostic biomarkers in determining survival outcome in colorectal cancer." (PMID 26633805, 2015). "In colorectal cancer, HLA-G was observed to aggregate at the invasion front in cancer foci, which was conducive to the formation of an immunosuppressive microenvironment, favoring further invasion and metastasis." (PMID 38310272, 2024). "Increased soluble HLA-G (sHLA-G) levels have been reported in patients with melanoma, neuroblastoma, lymphoproliferative disorders, breast, ovarian and colorectal carcinoma when compared to healthy controls or subjects with benign neoplasms." (PMID 39703498, 2024). "SPP1-expressing macrophages have been demonstrated to influence the invasive potential of colorectal cancer cells via HLA-G." (PMID 38067407, 2023). "Human leukocyte antigen-G (HLA-G) has been reported to be aberrantly expressed in colorectal cancer (CRC); however, its prognostic value remains controversial." (PMID 37875821, 2023). "HLA-G is a significant prognostic indicator of colorectal cancer, and the possible mechanism is the binding of HLA-G to its suppressive immune checkpoints ILT-2 and ILT-4." (PMID 38041084, 2023). "Our results of HLA-G expression as a prognostic marker are in accordance with previously published studies on patients with colorectal cancer." (PMID 35027037, 2022). "A similar intratumoral heterogeneity of HLA-G expression was also shown in colorectal cancer (CRC) using different HLA-G specific antibodies." (PMID 35185904, 2022). "HLA-G is a known ligand for CD8αα, which is expressed on some colorectal cancer, while HLA-E is mainly expressed in human endothelial cells and is highly expressed in tumor cells." (PMID 34759930, 2021). "For an example, the inter-patient proportion of HLA-G expression in cancers has been observed from 24 to 94.1% in breast cancers, and from 22.1 to 70.7% in colorectal cancers." (PMID 34276691, 2021). "Consistent with the present results, the findings of a previous study revealed coexpression of HLA-G and ILT4 in primary colorectal cancer (CRC) and identified its association with advanced stage and poor OS." (PMID 34276642, 2021). "Investigation of the HLA-G promoter region and part of the CpG island in colorectal cancer cell lines and choriocarcinoma cell lines have further showed a discrepancy between methylation level and HLA-G expression." (PMID 32560316, 2020). "In this study, lesion HLA-G expression in 379 case-matched serial section primary colorectal cancers (CRC) were evaluated with mAb 4H84 (recognizing an epitope in HLA-G α1 domain), and mAb 5A6G7 (recognizing an epitope encoded by intron 4), respectively." (PMID 30234020, 2018). "In our study, mAbs 4H84 and 5A6G7 were used to analyze the HLA-G expression by immunohistochemistry in primary colorectal cancer (CRC) samples." (PMID 30234020, 2018). "In this study, expression and predictive relevance of HLA-G expression in 457 primary colorectal cancer (CRC, ncolon = 232, nrectal = 225) patients was investigated." (PMID 29296176, 2017).